DUSP19 (dual specificity phosphatase 19)
Description:
Has a dual specificity toward Ser/Thr and Tyr-containing proteins.
Synonyms: DUSP17; LMWDSP3; SKRP1; TS-DSP1
Tractability: No criterion of Open Targets' tractability assessment is met for any kind of drug.
Gene: Protein-coding gene on chromosome 2 (183,078,559 to 183,100,008, forward strand). Ensembl gene ENSG00000162999.
Subcellular location (Human Protein Atlas): Nucleoplasm
Gene Ontology:
Molecular function: protein binding; protein serine/threonine phosphatase activity; protein tyrosine phosphatase activity; protein tyrosine/serine/threonine phosphatase activity; JUN kinase phosphatase activity; MAP-kinase scaffold activity; mitogen-activated protein kinase kinase kinase binding; protein kinase activator activity; protein kinase inhibitor activity
Biological process: negative regulation of JNK cascade; positive regulation of JNK cascade; positive regulation of MAPK cascade; regulation of JNK cascade; MAPK cascade
Cellular component: cytoplasm
Genetic constraint (gnomAD): Loss-of-function variants: 17 observed, 16.78 expected, observed/expected ratio (o/e) 1.01, 90% interval 0.69 to 1.52. The upper end of that interval is the gene's LOEUF score, 1.52, which puts it in group 6 of 6, group 1 being the genes least tolerant of losing a copy. Missense variants: 253 observed, 263.94 expected, observed/expected ratio (o/e) 0.96, 90% interval 0.86 to 1.06. Synonymous variants: 80 observed, 94.28 expected, observed/expected ratio (o/e) 0.85, 90% interval 0.71 to 1.02.
Homologues: Orthologues: chimpanzee DUSP19 (100% identical), macaque DUSP19 (99% identical), pig DUSP19 (90% identical), rabbit DUSP19 (90% identical), guinea pig DUSP19 (88% identical), mouse Dusp19 (82% identical), dog DUSP19 (79% identical), tropical clawed frog dusp19 (66% identical), zebrafish dusp19a (59% identical), zebrafish dusp19b (58% identical). Paralogues in human: DUSP10 (32% identical), DUSP4 (29% identical), DUSP1 (29% identical), DUSP2 (29% identical), DUSP9 (29% identical), SSH1 (29% identical), DUSP7 (28% identical), DUSP16 (28% identical), DUSP5 (27% identical), DUSP8 (27% identical), SSH2 (27% identical), SSH3 (27% identical), and 19 more.
Diseases named in the same sentence as DUSP19 in open-access papers:
DUSP19 is named in the same sentence as 5 diseases in open-access papers, as found by Europe PMC text mining. Sharing a sentence is not in itself a finding about the gene and the disease. The quoted sentences say what the papers report.
colorectal cancer (1 paper, 2021). A primary or metastatic malignant neoplasm that affects the colon or rectum. "The subnetworks revealed genes that are previously reported as CRC-associated as well as several yet undeciphered genes that may contribute colorectal cancer, such as DNAAF5, RASL10B, DUSP19, and TTC27." (PMID 34790220, 2021).
DUSP19 also shares sentences with these, for which no sentence is quoted: pancreatic neuroendocrine tumor (2 papers); asthma (1); cancer (1); osteoarthritis (1).